U3 (Small nucleolar RNA U3 )
Synonyms: LOC124906378
Gene: Small nucleolar RNA gene on chromosome 3 (45,255,409 to 45,255,620, reverse strand). Ensembl gene ENSG00000202268.
Gene Ontology:
Biological process: RNA processing
Cellular component: nucleolus
Homologues: Orthologues: chimpanzee U3 (98% identical), macaque U3 (85% identical). Paralogues in human: SNORD3P1 (85% identical), U3 (83% identical), U3 (82% identical), SNORD3G (81% identical), SNORD3E (80% identical), U3 (80% identical), SNORD3D (79% identical), SNORD3H (79% identical), U3 (78% identical), U3 (77% identical), U3 (76% identical), U3 (75% identical), and 10 more.